TIGIT (T cell immunoreceptor with Ig and ITIM domains)
Diseases named in the same sentence as TIGIT in open-access papers (continued):
Sharing a sentence is not in itself a finding about the gene and the disease.
tumor (continued). "By acquiring TIGIT expression, MCL cells may evade tumor immune surveillance via the TIGIT-CD155-CD226 axis to suppress the cytotoxic function of T and NK cells." (PMID 36163179, 2022). "We previously observed that the anti-tumor efficacy of combined anti-PD-L1 and anti-TIGIT blockade in mice is abrogated by a CD226-blocking mAb, suggesting that costimulation by both CD226 and CD28 is required to overcome inhibition by PD-1 and TIGIT." (PMID 35263569, 2022). "TIGIT blockade is a promising immunotherapy for cancer when combined with PD-1/PD-L1 blockade, while it does not significantly inhibit tumor growth when administrated alone." (PMID 35320940, 2022). "An exhaustion signature of 28 genes, including TIGIT, TNFRSF9/4-1BB, and CD27, was identified in exhausted T cells in melanoma tumours and was also found to be upregulated in high-exhaustion cells in most tumours." (PMID 36154923, 2022). "To comprehensively inspect the immune microenvironment of HCC TME, we firstly compared gene expression of immune inhibitory checkpoint molecules between tumor tissues and normal (peri-tumor) tissues, including CD274, CTLA4, HAVCR2, LAG3, PDCD1, PDCD1LG2, TIGIT, and SIGLEC15." (PMID 35444645, 2022). "The depletion of T cells cannot effectively recognize tumor antigens and conversely, exhausted T cells with high expression of inhibitory molecules such as PD-1, TIGIT, and TIM-3 gradually lose their proliferation and cytotoxic capacity and further promote tumor progression." (PMID 35712507, 2022). "Moreover, genetic- or biologics-based co-blockade of TIGIT and CD96 has been shown to improve tumor control while co-blockade of TIGIT and PVRIG has also been shown to promote NK cell function." (PMID 35812451, 2022). "Furthermore, it was found that elevated TIGIT on CD3 T cells led to functional defects and impaired glucose metabolism and that blocking TIGIT restored CD3 T cell activity and inhibited tumor growth." (PMID 35911673, 2022). "The anti-tumor effect of ICIs targeting LAG-3, TIM-3 or TIGIT in humans is currently under study." (PMID 35541908, 2022). "TIGIT has many ligands, CD155 (PVR or Necl-5), CD112 (nectin-2, also known as PRR2 or PVRL2), and CD113, CD155, CD112, CD113, and CD111, which are expressed in APCs or tumor cells." (PMID 35669786, 2022). "Among them, CTLA4, TIGIT, TNFRSF4 and TNFRSF18 were highly expressed in tumor-infiltrating Tregs." (PMID 35562760, 2022). "Blocking Abs that target TIGIT and CD155 interaction could up-regulate NK functions and inhibit tumor growth in a mouse model." (PMID 35464486, 2022). "TIGIT also suppresses anti-tumor immunity by TCR downregulation upon the binding to the ligands, CD155 (PVR) and CD112 (Nectin2), expressed in myeloid cells and tumor cells." (PMID 36211375, 2022). "TIGIT and TIM-3 inhibitory receptors were specifically increased in TIL and not in NIL CD4 and CD8 T cells, suggesting that the tumor microenvironment plays a crucial role in inhibiting tumor-specific T-cell responses." (PMID 36341402, 2022). "Enhanced tumor lysis and NK degranulation were only observed when KIR2DL5 was blocked, either alone or with TIGIT blockade, suggesting that KIR2DL5 has a dominant role over TIGIT in inhibiting KIR2DL5+TIGIT+ NK cell cytotoxicity." (PMID 36377656, 2022). "TIGIT and PD-1 may also be co-expressed by CD103+ CD8+ resident memory T cells (Trm), a T cell subpopulation that mediates anti-tumor immunity that may be derived from stem cell-like memory T (Tscm) or effector T (Teff) cells." (PMID 35263569, 2022). "Although TIGIT and PD-1 dual blockade alone did not seem to impact tumor growth, combining neoantigen vaccine substantially suppressed tumor growth and led to longer survival of tumor-bearing animals." (PMID 36569934, 2022). "TIGIT competes with the co-stimulatory receptor CD226 in T-cells to bind CD155 on APCs which become tolerogenic, cannot activate T-cells, and release IL-10 inhibiting of Teff cell anti-tumor responses." (PMID 35874729, 2022).
tumor (continued). "TIGIT, a co-inhibitory signaling molecule on the surface of a variety of T cells including CD8+ tumor infiltrating lymphocytes and regulatory T cells (Tregs), may dampen the anti-tumor immune response." (PMID 35716328, 2022). "And the tumor progression does not trigger changes in the immune landscape related to TIGIT upregulation." (PMID 35320940, 2022). "In addition, since FREM2 mutation was associated with immune infiltration, we analyzed its association with the expression levels of PDCD1, CD274, CTLA4, LAG3, TIGIT, and HAVCR2, which are important immune checkpoints responsible for tumor immune escape." (PMID 35252356, 2022). "In addition to affecting immune effector function, hypoxia, plus continuous tumor antigen stimulation, can also induce expressions of exhaustion markers TIM-3 and TIGIT, which is HIF1α-independent." (PMID 35840558, 2022). "Furthermore, according to a recent study, TIGIT is expressed on tumor-infiltrating NK cells, and TIGIT blockade reverses the exhaustion of NK cells independently of the adaptive immune system, namely, CD8+ T cell-mediated tumor reactivity." (PMID 35320940, 2022). "Moreover, the frequency of tumour-infiltrating CD3+CTLA-4+, CD8+PD-L2+, CD8+TIGIT+, CD8+A2aR+ cells positively correlated with lymphovascular invasion (p = 0.03, p = 0.03 and p = 0.03)." (PMID 35366537, 2022). "In our setting, OX alone did not exert any therapeutic effect; however, as expected, anti-TIGIT mAb alone showed a slight inhibition of tumor growth but failed to extend the survival of CT26-bearing mice." (PMID 36389751, 2022). "Thus, full restoration of CD226 signaling, and optimal anti-tumor CD8+ T cell responses, requires blockade of TIGIT and PD-1, providing a mechanistic rationale for combinatorial targeting in the clinic." (PMID 35263569, 2022). "TIGIT interaction with NECTIN inactivates T and NK effector function, which the tumor could exploit for immune evasion." (PMID 35995947, 2022). "These additional ICs include PD-1, TIM-3, TIGIT, CD96, LAG3, CD161, Siglec-7, and IRp60 and can be up-regulated or de novo expressed by NK cells in pathologic conditions, thus contributing to avoid exacerbated immune responses and also favoring tumor escape." (PMID 35891197, 2022). "Clinically, dual blockade of TIGIT and PD-1 could increase the frequency of CD8+ TILs and tumor antigen specific CD8+ T cells in established melanoma patients." (PMID 36159789, 2022). "Dual blockade of CD96 with PD-1, PD-L1, TIGIT, or CTLA-4 increases antitumor response, and triple blockade of CD96, PD-1 and TIGIT yields the highest level of antitumoral immunity in various mouse tumor models." (PMID 35164813, 2022). "Our data revealed that the addition of TIGIT blockade to MWA upregulated the expressions of CXCL9 and CXCL10 in TAMs and the expression of their receptor CXCR3 in T cells, which might restrain tumor growth and enhance antitumor immunity." (PMID 35320940, 2022). "Among the top enriched signaling pathway network, the interactions between THBS2+ CAFs and other cells within the tumor micro-ecosystem were most mediated by THBS, followed by stromal/immune signaling pathways, e.g. THY-1, FN-1, TGF-β, IL6/4, MHC-I, VEGF, CD40, or TIGIT." (PMID 35547750, 2022). "Interestingly, both KCC2 and NKCC1 are significantly related to tumor-infiltrating immune cells, including tumor purity and immune checkpoint molecules such as PD-L1, CTLA-4, LAG-3, and TIGIT in ccRCC." (PMID 35372048, 2022). "Some inhibitory receptors and checkpoint molecules, such as NKG2A, TIGIT, and CBLB, blocking the NK cell activation, can be knocked out by CRISPR/Cas9 gene-editing technology to increase the anti-tumor cytotoxicity of NK-92 cells clones used for modification with CAR constructs." (PMID 36612114, 2022). "Moreover, the authors also observed TIGIT and TIM3 co-expression in PBLs, MALs, and TILs but with a decreased frequency in tumor proximity." (PMID 35656508, 2022).
tumor (continued). "When TIGIT interacts with its primary ligand CD155 on DC or cancer cell membranes or with CD112 expressed by tumor cells and APC in the tumor microenvironment, it induces a decrease in the proinflammatory cytokine secretion, proliferation, and killing function of immune cells." (PMID 36612180, 2022). "The expression of TIGIT in various immune cells was up-regulated after MWA, and the addition of TIGIT blockade to MWA prolonged survival and delayed tumor growth in the MC38 tumor model." (PMID 35320940, 2022). "The acquisition of TIGIT expression on tumor cells is MCL-specific and has not been reported in other CAR T-treated diseases." (PMID 36163179, 2022). "As these molecules have the peculiar feature of binding both DNAM-1 and TIGIT, an inhibitory receptor on NK cells, the expression of CD112 and CD155 by tumor cells could potentially play a dual role either by triggering or dampening NK cell effector functions." (PMID 34203391, 2021). "A blockade of receptor–ligand interaction by targeting TIGIT or PVR could reverse the exhaustion of NK and CD8+ T cells and enhance the anti-tumor immunity." (PMID 34068552, 2021). "These genes were defined as the tumor reactive signature (TRS), including co-inhibitory receptors (CTLA4, PDCD1, TIGIT and HAVCR2), reactive markers (CD38 and ENTPD1), effector molecules (NKG7 and PRF1), tumor necrosis factor TNFRSF9 and critical exhaustion-related regulator TOX." (PMID 34804045, 2021). "TIGIT can interact with poliovirus receptor (PVR, CD155) on DCs to induce IL-10 secretion for suppressing the Th1 T-cell response, inhibiting the NF-κB pathway and preventing the effective cytotoxic immune response, which is required to reject the tumour." (PMID 34445385, 2021). "Multiple investigations have uncovered the inhibitory checkpoint inhibitors expressed on NK cells in tumor microenvironment, including the famous PD-1, CTLA-4 as well as newly identified NKG2A, TIGIT, which are now appreciated as promising targets for NK cells-based immunotherapy." (PMID 33262461, 2021). "Additionally, tumor resident CD103+ NK cells express more inhibitory receptors, such as TIGIT and TIM-3, as compared with recruited NK cells, indicating the undermined NK-mediated immunosurveillance in TME." (PMID 35008589, 2021). "Furthermore, detailed mechanisms of anti-tumor immunotherapy, including blocking PD-1(L1), LAG-3, TIM-3, and TIGIT, are still unclear and require further research." (PMID 33717059, 2021). "Targeting tumor infiltrating Tregs may be achieved using antibodies to TIM-3, LAG-3, TIGIT, VISTA, and CD73." (PMID 34806028, 2021). "The overall survival of tumor-bearing mice has been further increased following treatment with both anti-TIGIT and anti-PD-L1 antibodies, suggesting that non-redundant mechanisms exist between these two pathways." (PMID 34885076, 2021). "We found TIGIT to be exclusively expressed by mononuclear immune cells with absent immunoreactivity in the tumor epithelium and a mostly granular cytoplasmic staining pattern." (PMID 33918309, 2021). "TIGIT blockers can effectively restore and enhance CD8+-mediated anti-tumor immune activity." (PMID 34938753, 2021). "In addition to HLA-specific inhibitory and activating NK receptors—Killer-cell immunoglobulin-like receptors (KIRs), NK cells express inhibitory receptors including PD-1, TIGIT, CD96, TIM-3 and CD161 for anti-tumor activity." (PMID 34572387, 2021). "Additionally, tumor cells express several inhibitory molecules such as T-cell immunoglobulin and ITIM (TIGIT), T-cell immunoglobulin and mucin-domain containing-3 (TIM-3), B- and T-lymphocyte attenuator (BTLA), or CD16060." (PMID 34702924, 2021). "However, during tumor progression liver resident NK cells in tumor tissue down regulate NKG2D and express inhibitory receptors PD-1, CD96, and TIGIT and are rapidly exhausted." (PMID 34071188, 2021).
tumor (continued). "In HCC-bearing mice which were resistant to PD-1 blockade, dual blockade of TIGIT and PD-1 expanded the effector memory CD8+ T cell population and increased ratio of cytotoxic T cells to Treg in tumors, resulting in suppressed tumor growth and prolonged survival." (PMID 34367161, 2021). "In conclusion, our platform for discriminating the tumour profiles of three IRs, LAG-3, TIM-3, and TIGIT, may have an impact on predicting both outcome and the immune microenvironment in RCC." (PMID 34545095, 2021). "TIGIT expression, but not PD-1 or CTLA-4, was found to be upregulated on exhausted NK cells and was associated with tumor progression in severe combined immunodeficient mice." (PMID 33946954, 2021). "In addition, LAG3 and TIGIT are usually coexpressed and upregulated along with PD1 on tumor-infiltrating lymphocytes (TILs)." (PMID 34249711, 2021). "Furthermore, TIGIT expression has been detected on Tregs and TIGIT+ Tregs suppresses the immune system via improving the expression of the co-inhibitory receptor, TIM-3, in tumor tissue." (PMID 32902664, 2021). "Moreover, in Treg-mediated tumor immune escape, Tregs express relatively high levels of TIGIT and low levels of CD226 compared with effector T cells (Teffs), resulting in a high ratio of TIGIT/CD226 expression and accelerating tumor development." (PMID 33549054, 2021). "TIGIT interacts with ligands CD115 and CD112 expressed on tumor cells." (PMID 34925314, 2021). "Moreover, PVRL1 (CD111, nectin-1) promotes TIGIT-mediated T cell suppression by stabilizing CD155 on the surface of HCC tumor cells, and PVRL1 knockdown in tumor cells in an HCC mouse model resulted in reduced tumor growth in a CD8+ T cell-dependent manner." (PMID 34367161, 2021). "However, anti-TIGIT/anti-PD-1 co-blockade increased IFN-γ, TNF-α and IL-2 in CD8+ TILs and resulted in complete tumor regression in all mice." (PMID 34367161, 2021). "Nevertheless, single TIGIT blockade achieved no or moderate anti-tumor efficacy in experimental tumor models and in enhancing in vitro functionality of human tumor-infiltrating CD8+ T cells." (PMID 34367161, 2021). "TIGIT is a T-cell immunoreceptor with Ig and ITIM domains, which was recently identified as an attractive cancer immunotherapy target due to its central role in tumor immunosurveillance." (PMID 33564068, 2021). "We examined the expression of TIGIT and NECTIN2 in the lymphocytes and tumor cells, respectively." (PMID 34140495, 2021). "In addition, immune checkpoints including PD-L1, HAVCR2, TIGIT, and LAG3 in the high-risk group were also higher than those in the low-risk group, which indicated that patients in the high-risk group might belong to the “hot” tumor that was tended to benefit from immune checkpoint inhibitor therapy." (PMID 35027921, 2021). "TIGIT is expressed by activated T-cells, NK cells, and Tregs, and its ligands include CD112 (NECTIN2) and CD155 (Necl-5), which are expressed by tumor cells and APCs within the tumor microenvironment (TME)." (PMID 34943817, 2021). "Studies in tumor-bearing Tigit+/+ and Tigit−/− mice demonstrated increased TIGIT expression on tumor infiltrating lymphocytes and lack of TIGIT in Tregs to be critical for immune suppression in tumor microenvironment." (PMID 34572463, 2021). "In line with this concept, we showed that ICs are sequentially acquired by tumor–specific CD8 T cells at the tumor site, leading to a terminally exhausted population characterized by TIM-3 expression, the latter being acquired at late stages after PD-1, TIGIT, and CTLA-4 expression acquisition." (PMID 33332284, 2021). "TIGIT binds to its ligand PVR or CD155 on the tumour cells with a much higher affinity than its activating counterpart CD226 (DNAM-1), thereby inhibiting the interaction between CD226 and CD155 which is widely expressed on tumour cells." (PMID 33995362, 2021). "In addition, blockaded TIGIT prevented NKT cell exhaustion, and promoted NKT cell-dependent tumor immunity in several tumors." (PMID 34745098, 2021).
tumor (continued). "In murine models of CT26 colorectal carcinoma, monotherapy with anti-TIGIT therapy did not effect tumor growth; however, when introduced with anti-PD-1 it resulted in a reduction of tumor growth." (PMID 33732652, 2021). "A TIGIT/PVR blockade could reverse the exhaustion of both T cells and NK cells, resulting in significant and durable anti-tumor effects." (PMID 34068552, 2021). "Although mouse TIGIT+ NK cells infiltrating CT26 tumors appear less functional than their TIGIT- counterparts, as shown by decreased production of IFN-γ and TNF-α as well as decreased degranulation, it should be noted that CT26 tumor cells express TIGIT ligand CD155." (PMID 34503073, 2021). "Tumor-infiltrating Tregs have been shown to exhibit a distinct signature comprising the co-stimulatory molecules (OX40, 4-1BB), cytokine receptors (IL1R2, IL21R, CCR8, CD30), and co-inhibitory molecules (PD-L1, TIGIT)." (PMID 33527196, 2021). "In both subcutaneous and ascites tumor models, the CD8+ T cell infiltration of mice treated with VV-α-TIGIT was much higher than that of mice treated with PBS, indicating that VV-α-TIGIT has a strong function of recruiting T cells, making the “cold” tumors “hot”." (PMID 33581644, 2021). "Therefore, we evaluated the relationship between the expression of immune inhibitory molecules (TIGIT, PDCD1LG2, PDCD1, LAG3, HAVCR2, CTLA4, and CD274) in the immune ignorant, immune inactive, and hot tumor subtypes." (PMID 33777927, 2021). "On the other hand, there are reports that TIGIT expression on circulating NK-cells (cNK) does not change in patients with other neoplastic diseases such as AML, pancreatic cancer and hepatocellular carcinoma." (PMID 34276685, 2021). "Study has suggested that CD96 could synergize with TIGIT to inhibit the antitumor response in tumor-bearing mouse models with lung metastasis, as the antitumor effect of CD96 blockade is higher in Tigit−/− mice." (PMID 33680972, 2021). "TIGIT is an inhibitory receptor that can decrease T cell and natural killer cell function by interacting with CD155 expression in the antigen-presenting cell or tumor cell." (PMID 34844217, 2021). "TIGIT (T cell immunoglobulin and ITIM domain) is a co-inhibitory receptor that acts as an important immune checkpoint, as it limits both T cell-driven inflammation and T cell and NK cell-dependent anti-tumor immunity." (PMID 32152316, 2020). "However, inhibition of DNAX accessory molecule-1 (DNAM-1) reduced the elevated anti-tumor activity and IFN-γ level by TIGIT blockade." (PMID 32882824, 2020). "CD155 is a ligand for DNAM-1, TIGIT, and CD96 and is involved in tumor immune responses." (PMID 32040157, 2020). "As with the MC38 tumors, TIGIT KO mice did not demonstrate any reduction in tumor take when implanted with B16F10 cells as compared to WT mice." (PMID 33117369, 2020). "This review will explore the function of CD155 within GBM as it relates to tumor migration and NK cell immunoregulation, as well as pre-clinical and clinical targeting of CD155/TIGIT and the potential that this pathway holds for the development of emerging NK cell-based immunotherapies." (PMID 32532329, 2020). "Since that the TIGIT/PVR immune checkpoint axis plays a major role in the functional regulation of T cells and NK cells, we also explored the role of CD4+, CD8+ T and NK cells in the tumor inhibition mediated by liothyronine therapy." (PMID 32894141, 2020). "Contrary to previous work by others, we do not observe a depletion of Treg as part of the anti-tumor mechanism of anti-TIGIT antibodies." (PMID 33117369, 2020). "Interestingly, a small subset of genes enriched in tumor Treg cells such as CTLA4, TIGIT, TNFRSF9, CD27, and LAYN are also highly expressed by exhausted tumor‐infiltrating CD8+ T cells reflecting a shared program of activation and exhaustion in these cells." (PMID 32272497, 2020). "In addition, TOX knockdown in TI CD8+ T cells from human tumor reduced the number of cells expressing PD-1, TIM-3, TIGIT, and CTLA-4." (PMID 32111241, 2020).